GBP1 (guanylate binding protein 1)
Diseases named in the same sentence as GBP1 in open-access papers (continued):
Sharing a sentence is not in itself a finding about the gene and the disease.
cancer (52 papers, 2008 to 2026). A tumor composed of atypical neoplastic, often pleomorphic cells that invade other tissues. "In this study, we used the RNA-seq and clinical data from The Cancer Genome Atlas (TCGA) database and four immunotherapy cohorts to evaluate the association between GBP1 expression and the efficacy of immunotherapy in pan-cancer patients." (PMID 35222540, 2022). "Both stromal and ESTIMATE scores were positively associated with GBP1 expression in 33 cancer types." (PMID 35222540, 2022). "This study found that GBP1 expression was positively associated with the expression of nine immune checkpoints in most cancer types." (PMID 35222540, 2022). "Similarly, GBP1‐5 showed strong positive associations with the Th1 cell recruiting in the cancer‐immunity cycle, while GBP6‐7 had weak correlations with this step." (PMID 37551111, 2023). "However, the underlying mechanism of GBP1/hsa-miR-30d-5p/GBP1P1 axis function in cancer needs further investigations." (PMID 38072995, 2023). "Moreover, other GBPs, the close relatives of GBP1, were reported to be associated with the malignancy of tumors and the prognosis of cancer patients." (PMID 35222540, 2022). "In addition, RNA-sequencing analysis revealed that loss of BARD1 results in the upregulation of GBP1 (guanylate-binding protein 1), a protein whose expression is associated with variable response to therapy depending on the adult carcinoma subtype examined." (PMID 36187937, 2022). "In addition, GBP1 was also observed to be associated with drug resistance and radioresistance in cancer cells." (PMID 31998647, 2019). "The parent gene GBP1 is known to be the mediator of the anti-proliferative effect of inflammatory cytokines in endothelial cells, and is implicated in several types of cancer according to GeneCards." (PMID 25765044, 2015). "Cancer emerges from a complex interplay of mutational events and cell state transitions that are accompanied by interferon-mediated inflammation and cytoskeletal reorganization which may involve GBP1 in the oncogenic process." (PMID 32117203, 2019). "In order to further investigate the cancer-promoting mechanism of GBP1, we tried to find a reliable pathway." (PMID 38167153, 2024). "PDCD1, CD274, CTLA4, LAG3, C10orf54, and BTLA expression had positive correlations in most cancer types, and in approximately half of the cancer types, GBP1 expression is positively correlated with CD276 expression." (PMID 35222540, 2022). "The pan-cancer analysis demonstrated that GBP1 was differentially expressed between tumors and normal tissues across many cancer types." (PMID 35222540, 2022). "To exclude the possibility that this difference was driven by a few cancer types with numerous patients, we compared the GBP1 expression of three clusters in each cancer type." (PMID 35222540, 2022). "The IPS in pan-cancer patients with high GBP1 expression was higher than those with low GBP1 expression." (PMID 35222540, 2022). "To determine the potential role of GBP1 expression in cancer immunotherapy, we investigated the correlation between GBP1 expression and some biomarkers such as immune checkpoints and TMB." (PMID 35222540, 2022). "Among the members of the GTPase family, guanylate binding protein 1 (GBP-1) is the most thoroughly studied member of many human cancers." (PMID 35836256, 2022). "Given the varied effects of GBP1 in cancer as detailed earlier, we next sought to determine the functional role(s) of GBP1 expression in PSaRC318 cells." (PMID 36187937, 2022). "In this study, we comprehensively analyzed GBP1 in a total of 33 cancer types in TCGA and proposed GBP1 expression as a novel biomarker for immunotherapy response." (PMID 35222540, 2022). "Most recently, GBP-1 was identified as a predictive marker for improved immunotherapy response in an analysis of multiple cancer types." (PMID 35681772, 2022).
cancer (continued). "To compare the enrichment degree of GBP1-related terms and pathways in different cancer types, we performed GSEA for each cancer type." (PMID 35222540, 2022). "In fact, GBP1 and GBP4 were associated with a favorable prognosis in 4 types of cancer (CRC, SKCM, BC, and STC) according to the Pathology Atlas analysis." (PMID 32265897, 2020). "Our results showed that higher mRNA expressions of GBP1 were found in HNSCC tissues, and that mRNA expression of GBP1 was significantly related with patients’ cancer stages and abundance of immune infiltrates." (PMID 32269280, 2020). "We first contrast the transcriptional levels of GBPs in cancers and normal samples and significantly higher mRNA expressions of GBP1/4/5 were found in HNSCC tissues in multiple datasets." (PMID 32269280, 2020). "In our study, we characterized a MA signature consisting of three distinct genes (Cxcl11, Gbp1, Ido1), which correlates with the presence of M1 macrophages and mature DC in various cancer cohorts available in TCGA." (PMID 32486450, 2020). "Multivariate analysis suggested that N-stage (HR = 1.33, 95% CI: 1.03–1.72, P < 0.05), high expressions of GBP1 and low expression of GBP6/7 were linked to shorter OS of cancer patients." (PMID 32269280, 2020). "Increasing evidence indicates an important role of GBP1 in cancer cell growth, invasion/migration and metastasis." (PMID 31998647, 2019). "It exhibited a significantly suppressed growth capacity in the GBP1 KO cells compared with the control cells and proved the deletion of GBP1 gene resulted a significantly higher chemosensitivity of the cancer cells." (PMID 31998647, 2019). "Analysis of three independent experiments showed that co-culture of ErbB2-P with activated T cells induces a significant increase in Gbp1 expression levels in the cancer cells." (PMID 29350274, 2018). "Future experiments should include human (colon) cancer cell lines with an even higher Sep15 expression than HT29 cells, which we would anticipate to have significantly increased GBP-1 levels as a response to loss of Sep15." (PMID 22254125, 2011). "Based on these findings and the prognostic outcomes based on the GBP1 expression profile in our study, GBP1 may also be a potential therapeutic target for other types of cancer." (PMID 40018406, 2025). "IFN-α/β/IFN-γ/IL-15 pathways were associated with improved survival and response in patients treated with ICIs, and GBP1 could serve as a surrogate to IFN-α/β/IFN-γ/IL-15 activity in pan-cancer scale analysis." (PMID 38758367, 2024). "These discoveries highlight the considerable prognostic implications of GBP1 in a pan-cancer." (PMID 37796192, 2023). "The effect of GBP1 expression in cancers appears to be complex." (PMID 38067341, 2023). "Additionally, we conducted a pan-cancer analysis to examine the influence of GBP1 on cancer prognosis." (PMID 37796192, 2023). "An extensive investigation into the expression pattern of GBP1 in pan-cancer was conducted." (PMID 37796192, 2023). "Higher immune scores were related to higher GBP1 expression in 32 cancer types except for THYM." (PMID 35222540, 2022). "GBP1 expression positively correlated with IPS in 16 cancer types." (PMID 35222540, 2022). "GBP1 expression negatively correlated with TIDE scores in 31 cancer types apart from THYM and DLBC." (PMID 35222540, 2022). "However, in a variety of other cancers with growth factor–driven gene signatures, GBP-1 promotes cell motility and poor prognosis." (PMID 35681772, 2022). "In the context of cancer, the effects of GBP1 appear to be highly complex." (PMID 35222540, 2022). "Distinct correlations existed between GBP1 expression and prognosis in cancer patients." (PMID 35222540, 2022). "The results suggested that GBP1 expression might be a predictive biomarker for pan-cancer patients receiving immunotherapy." (PMID 35222540, 2022). "Moreover, the difference of IPS between high and low GBP1 expression groups was significant in 17 cancer types." (PMID 35222540, 2022).
cancer (continued). "Furthermore, GBP1 expression can be a potential biomarker for immunotherapy response, facilitating the identification of suitable patients for tailoring optimal cancer therapeutic strategies." (PMID 35222540, 2022). "GBP1 may restrain cancer cell proliferation as it inhibits endothelial and epithelial proliferation after cytokine stimulation." (PMID 35222540, 2022). "The transcripts included in the final signature were BCL10, CXCL11, CYBB and GBP1 and, based on their expression levels, our algorithm was able to classify plasma samples into cancer and control with a receiver operating characteristic (ROC) area under the curve (AUC) of 0.92 to 0.95." (PMID 33580122, 2021). "GBP1 is a potential target for cancer inflammatory responses." (PMID 33123584, 2020). "Since high respiratory reserve capacity and ATP production are always linked to high mitochondrial fidelity, our results suggested that GBP1 gene KO impaired both mitochondrial oxidative phosphorylation and the compensatory glycolysis generally seen in cancer cells." (PMID 31998647, 2019). "And while GBP1 may act to restrain cancer cell proliferation in these cancers, it may also act as a mediator of treatment resistance." (PMID 32117203, 2019). "To evaluate whether the GBP1 gene knockout affected the sensitivity of cancer cells to chemotherapy, we assessed cell proliferative ability with different concentrations of docetaxel and paclitaxel applied in cell culture." (PMID 31998647, 2019). "To determine whether the GBP1 gene KO had an effect on cancer cell growth, we firstly used the IncuCyte ZOOM System to record the real-time phase-contrast images and growth curves of different cell lines." (PMID 31998647, 2019). "Sorted cancer cells were initially interrogated by qRT-PCR to analyze Gbp1 levels." (PMID 29350274, 2018). "Thus, Sep 15 appears to play a stimulatory role (possible oncogene) in cancer etiology in colonic tissue, whereas the possible links to GBP-1 and the apolipoproteins A-I and IV remain to be elucidated further." (PMID 23226526, 2012). "However, Cancer cells can evade the IFN-γ-based Th1 immune response through downregulated GBP1." (PMID 38753689, 2024). "However, the immunological effects of GBP1 in pan-cancer patients are still obscure." (PMID 35222540, 2022). "Furthermore, special attention has been put on the role of GBP1 in cancer pathology." (PMID 33123584, 2020). "We believe that GBP1 and HNRNPK bind to regulate the expression of CD44 protein through A3SS alternative splicing form, and finally play a role in promoting cancer." (PMID 38167153, 2024). "Because PIM1 showed a prominent effect on phosphorylation of GBP1 and is a known GBP1-interactor in cancer cells, we performed additional experiments with recombinant PIM1 and GBP1 to explore their interaction." (PMID 37797010, 2023). "Our study first provided evidence of the correlation between GBP1 and hot TME in the pan-cancer context." (PMID 35222540, 2022). "The results demonstrated that the expression of GBP1 and GBP5 were higher in HNSCC tissues, while the expression level of GBP6 was lower in cancer tissues." (PMID 32269280, 2020). "The current study and our previous study have provided strong evidence that GBP1 is significantly upregulated in GBM and plays a key role in GBM growth and invasion, but the functions of GBP1 in cancer appear to be cell-type specific." (PMID 26848767, 2016). "Among those significantly increased with BRAF+/−MEKi were 14 of 17 genes of a Th1 signature associated with immunologic rejection of cancer, with GNLY, IFNG, and GBP1 the only genes not represented." (PMID 41514118, 2026). "In 33 cancer types, TIGIT and HAVCR2 expression had positive correlations with GBP1 expression." (PMID 35222540, 2022). "Except for GBP1 and GBP2, the role of other GBPs, including GBP5, in the malignant evolution of cancers, particularly TNBC, remains unclear." (PMID 33916322, 2021).
cancer (continued). "Moreover, we also explored the expression of GBPs with cancer stage for HNSCC and we found GBP1/5/6 groups significantly varied, but GBP2/3/4/7 groups did not significantly differ." (PMID 32269280, 2020). "While GBP1 is anti-proliferative in normal cells, acting to restrain premature angiogenesis or IEC proliferation in inflammatory conditions, this effect is highly context-dependent in cancer." (PMID 32117203, 2019). "Further study indicated the IRF1 seemed to play a key role in the transcriptional activation of interferon-inducible guanylate binding proteins (GBP1 and GBP2), which subsequently induces T-lymphocyte immune response against the cancer cell spreading and proliferation." (PMID 27806724, 2016). "Conversely, GBP1 may contribute to the acquisition of invasion ability in non-invasive cancer cells, whereas it contributes to the promotion of cell proliferation in invasive cancer cells, that is, cells after acquiring invasiveness." (PMID 40018406, 2025). "In combination with existing reports and GBP1-regulated AS events, a regulatory pathway was finally obtained, that is, GBP1 regulated CD44 protein expression through A3SS alternative splicing after binding to HNRNPK, and finally played a role in promoting cancer." (PMID 38167153, 2024). "Although all results above are from patient samples or human cell lines, it must be noted that human GBP1 is more homologous to murine GBP2, a closely related GTPase, that bears special examination when using syngeneic murine cell lines for further study of GBP biology and cancer progression." (PMID 32117203, 2019). "Thus, a significant link between Sep15 and GBP-1 and possibly other GBP-isoforms may be important in human cancers, possibly beyond colonic epithelia." (PMID 23226526, 2012). "An innate immune signaling gene, GBP1, is also among the most downregulated and could play a role in the cancer’s ability to evade host immune rejection of non-self cells, an open question across all transmissible cancers." (PMID 39345472, 2024). "However, our experiment found that GBP1 was not a alternative splicing factor, so it was speculated that it plays a cancer-promoting role by binding with the true alternative splicing factors, and indirectly participates in the alternative splicing pathway." (PMID 38167153, 2024). "One aspect of this differential activity may be influenced by heterogeneous binding partners, such as the findings that GBP1 interacts directly with proto-oncogene serine/threonine kinase 1 (PIM1), a marker of disease progression and treatment resistance in ovarian and other cancers." (PMID 32117203, 2019). "To assess the effect of currently available therapeutic inhibitors targeting GBP1, we used NSC756093 that interrupts the interaction between GBP1 and proto-oncogene serine/threonine-protein kinase (PIM1), the inhibition of which could potentially revert paclitaxel resistance in cancer cells." (PMID 30303482, 2018).
bacterial infection (7 papers, 2018 to 2023). "GBP-1 is an inflammatory molecule and usually up-regulated during bacterial infection, inflammation outcomes and associated with apoptosis." (PMID 32117813, 2020). "LPS stimulation, which is increased during bacterial infection and metabolic stress, can also induce Gbp1 protein expression." (PMID 29374208, 2018). "While the biological functions of human and mouse GBP1 may differ, mGBP1 is clearly required for inflammasome activation during some bacterial infections." (PMID 36744765, 2023). "GBP1 acts a gatekeeper of microbe-induced macrophage apoptosis and pyroptosis, and IFNγ enhanced macrophage pyroptosis mediated by caspase-4 in a GBP1-dependent manner during bacterial infection, such as Shigella flexneri and Salmonella." (PMID 35682857, 2022).
adenocarcinoma (2 papers, 2020 to 2025). A common cancer characterized by the presence of malignant glandular cells. "In agreement with studies carried out in adenocarcinoma cell lines, we found similar upregulation of genes such as IDO1, GBP1, CXCL9, CXCL10, and CXCL11 in response to IFN-γ, all of which are also known to be upregulated in IBD patients." (PMID 33396621, 2020).
cardiovascular disease (2 papers, 2012 to 2022). "Additionally, 32 TR genes (including GBP1, IFI30, CSTB, ACTR2, etc.)were found within risk loci of cardiovascular disease (Fisher’s exact test, P = 0.394)." (PMID 35133977, 2022). "We recently investigated potential effects of GBP-1 on endothelial progenitor cell function and aimed to identify antiangiogenic mechanisms that could explain EPC dysfunction in the inflammatory state and associated cardiovascular disease." (PMID 23217187, 2012).
inflammation (1 paper, 2017). Aberrant reaction of the microcirculation characterized by movement of fluid and leukocytes from the blood into extravascular tissues. "Strikingly, some of these proteins, such as RhoA or guanylate-binding protein-1 (GBP-1) have been associated with gut inflammation and IBD." (PMID 29051760, 2017).
nervous system tumors (1 paper, 2021). "GBP1, 2, 3, 4, 5 were upregulated in the brain and nervous system tumors vs normal brain tissue, which was confirmed by data from 13, 7, 5, 1, and 1 datasets, respectively." (PMID 34759950, 2021).
GBP1 also shares sentences with these, for which no sentence is quoted: esophageal cancer (3 papers); hepatitis C (3); systemic lupus erythematosus (3); systemic sclerosis (3); colon adenocarcinoma (2); diabetes (2); diffuse large B-cell lymphoma (2); fibrosis (2); gastric adenocarcinoma (2); head and neck squamous cell carcinoma (2); idiopathic pulmonary fibrosis (2); infectious disease (2); lymph node metastasis (2); ovarian serous cystadenocarcinoma (2); Ovarian Tumors (2); psoriasis (2); testicular germ cell tumor (2); uterine carcinosarcoma (2); acute myeloid leukemia (1); adrenocortical carcinoma (1); brain cancer (1); cholangiocarcinoma (1); Crohn disease (1); cutaneous lupus erythematosus (1); Dengue hemorrhagic fever (1); endocervical adenocarcinoma (1); endocervical carcinoma (1); Epstein-Barr virus infection (1); fibromyalgia (1); head and neck tumors (1).
A further 40 diseases each share a sentence with GBP1 in 1 paper.